LINC01555 (long independently transcribed non-coding RNA 1555)
Synonyms: C1orf180; FLJ35487
Gene: Long non-coding RNA gene on chromosome 1 (84,628,230 to 84,635,020, reverse strand). Ensembl gene ENSG00000180869.
Diseases named in the same sentence as LINC01555 in open-access papers:
LINC01555 is named in the same sentence as 4 diseases in open-access papers, as found by Europe PMC text mining. Sharing a sentence is not in itself a finding about the gene and the disease. The quoted sentences say what the papers report.
colon cancer (1 paper, 2021). "Consistent with the results from TCGA, the expression of LINC01555 and FZD10-AS1 was significantly increased in left-side colon cancer tissues compared with right-side tissues, while the opposite results were observed for AC015712." (PMID 33858429, 2021).
colorectal cancer (1 paper, 2017). A primary or metastatic malignant neoplasm that affects the colon or rectum. "Most likely, LINC01555 could play substantial roles in the tumorigenesis and development of colorectal cancer via influencing cAMP signaling pathway." (PMID 28187432, 2017). "Therefore, the functional enrichment analysis may offer a clue for elucidating the role of LINC01555 and LINC01207 in carcinogenesis of colorectal cancer and the specific underlying molecular mechanisms." (PMID 28187432, 2017). "Third, the roles of LINC01555, RP11-610P16.1, RP11-108K3.1, and LINC01207 in colorectal cancer are unknown; in vitro and in vivo experiments are expected to answer this question." (PMID 28187432, 2017). "However, since the research on the clinical and biological function of LINC01555, RP11-610P16.1, RP11-108K3.1, and LINC01207 is still nonexistent in colorectal cancer patients, there is a lot of research that needs to be accomplished." (PMID 28187432, 2017).
gastric carcinoma (1 paper, 2021). A carcinoma that arises from epithelial cells of the stomach. "Linc01555 promotes proliferation, migration, and invasion of gastric carcinoma cells by interacting with the Notch signaling pathway." (PMID 33995377, 2021).
tumor (1 paper, 2021). "We found that the expression of LINC01555, AC015712, and FZD10-AS1 was associated with the tumor stage, but not with other clinical features." (PMID 33858429, 2021).